LATS2 (large tumor suppressor kinase 2)
Diseases named in the same sentence as LATS2 in open-access papers (continued):
Sharing a sentence is not in itself a finding about the gene and the disease.
cancer (109 papers, 2008 to 2025). A tumor composed of atypical neoplastic, often pleomorphic cells that invade other tissues. "The mechanism underlying LATS phase separation, as observed in the formation of the LATS2 signalosome, holds significant promise as a novel diagnostic and therapeutic strategy for cancer." (PMID 39757214, 2025). "Phase 1 clinical trials are currently assessing different YAP/TAZ-TEAD inhibitors in patients with mesothelioma and other cancers harboring NF2/LATS1/LATS2-mutations and tumors with functional YAP/TAZ fusions or otherwise elevated YAP/TAZ levels." (PMID 38538573, 2024). "It is of interest to address if pharmacological enhancement of LATS2 function in RB1-deficient cancer is feasible." (PMID 34359636, 2021). "In this scenario, in sharp contrast to SUCLA2, loss of LATS2 generates certain growth advantages to RB1-deficient cancer." (PMID 34359636, 2021). "Decreased expression of large tumor suppressor kinase 2 (LATS2) may cause cancer cells to become resistant to 5-FU chemotherapy." (PMID 38302953, 2024). "The association between LATS2 in the pathogenesis of cancers propose that their combination might be studied as a possible molecular marker for particular subgroups of patients." (PMID 32458634, 2020). "Therefore, LATS1 mutants (R657C, R694C and R697G) and LATS2 mutants (R623W and R645L), are expected to become inactive in human cancer due to loss of interactions with LATS activators such as MOB." (PMID 25482410, 2015). "Thus, in human malignant tumors, deficiency in Lats1 and/or Lats2 might promote overexpression of Cdc25B, leading to centrosome overduplication and, ultimately, to cancer progression." (PMID 26530630, 2015). "Among these, the top 60 proteins exhibiting significant p-values revealed high expression levels of phosphorylated AKT1, along with members of the STK family and LATS2 under the altered respiratory metabolism of cancer cells." (PMID 39922804, 2025). "Nuclear factor-κB (NF-κB) has been found to be closely related to exosome-mediated cancer progression, and this research further demonstrated that miR-105-5p-LATS2 significantly activates the NF-κB pathway, which is involved in NF-CAF transformation." (PMID 40151143, 2025). "This, in turn, enhances the expression of transforming growth factor-β (TGF-β), activates epidermal growth factor receptor (EGFR), and inhibits LATS1 and LATS2, leading to cancer cell proliferation." (PMID 40699764, 2025). "LATS2, a core component of the Hippo/YAP axis, has been implicated in various diseases including cancers." (PMID 39166861, 2024). "As the core kinase of the Hippo signaling pathway, LATS2 regulates cancer progression by affecting YAP1 activity." (PMID 39247829, 2024). "Melittin inactivated the YAP/HIF-1α pathway via up-regulation of LATS2, ultimately inhibiting cancer progression of NSCLC." (PMID 38889502, 2024). "Accordingly, miR-31-5p plays important role in cancer development by directly targeting large tumour suppressor kinase 2 (LATS2)." (PMID 36768818, 2023). "After miR-92 is taken up by cancer cells, it acts on the target gene large tumor suppressor kinase 2 (LATS2)." (PMID 36759842, 2023). "The link between LATS2 expression and OS was investigated using TCGA cohort to assess the value of LATS2 during cancer patient prediction." (PMID 36118851, 2022).
cancer (continued). "We first utilized the data obtained from TCGA in the TIMER data bank to assess the mRNA expression of LATS2 in pan-cancer." (PMID 36118851, 2022). "Following absorption by cancer cells, miR-92 targets large tumor suppressor kinase 2 (LATS2), which interacts with YAP1 and promotes the nuclear translocation of YAP1 in BC cells." (PMID 36499561, 2022). "The findings showed that LATS2 expression in numerous cancer groups was lower than that in the corresponding normal groups." (PMID 36118851, 2022). "We also propose that SMG6 and TERT are novel molecular target candidates for LATS2-inactivated cancers such as MM." (PMID 36335095, 2022). "In line with this, in gastric adenocarcinoma cells, highly expressed miR-372 produced the proliferation and migration of cancer cells by suppressing the LATS2." (PMID 34575133, 2021). "To explore the internal mechanism for LATS2 involvement in cancers, we investigated the PPI network for LATS2 using the GeneMANIA database and found that LATS2 interacted with YAP1." (PMID 34699318, 2021). "Genetic alteration and epigenetic modification of the Hippo pathway components are also observed in human cancers, such as the YAP amplification, mutation, and deletion of LATS2 and neurofibromatosis type 2 (NF2), and the promoter hypermethylation of LATS2." (PMID 34944834, 2021). "Previous oncological studies suggest that SKI interacts with several core Hippo pathway components, including LATS2; however, they utilized cancer cell lines (i.e., breast, kidney, and lung)." (PMID 33847835, 2021). "In hepatocellular carcinoma, LATS2 mediated yes-associated protein (YAP) phosphorylation and promoted nuclear localization of YAP1 and YAP1/TEAD2 interactions, which in turn induced cancer progression." (PMID 34699318, 2021). "LATS2-Wnt/β-catenin/DRP1/mitochondrial division is identified as a signaling pathway that promotes cancer cell death." (PMID 33462260, 2021). "Studies have reported that the expression levels of LATS1 and LATS2 proteins in malignant tumor tissues such as ovarian tumors and non-small-cell lung carcinoma are significantly lower than those in normal tissues." (PMID 32423384, 2020). "All six selected survival-related genes (EMP1, TPM1, NRP2, FGFR1, CAVIN1, and LATS2) were reported to play a positive role in disseminating cancer cells or invasion in many kinds of cancers." (PMID 32695477, 2020). "LATS2 was also reported to be regulated by many other microRNAs such as miR-93, miR-372, and miR-744 in different cancers." (PMID 33414893, 2020). "In this study, we demonstrate a novel drug-resistance mechanism in which miR-31-5p and its transcription factor regulate cancer cell growth and apoptosis by targeting LATS2." (PMID 31623173, 2019). "It remains thus to be tested if the ambiguous findings related to the involvement of LATS1/LATS2 and other Hippo pathway components in the control of epidermal homeostasis and cancer development reflect such cell-intrinsic differences between mice and humans." (PMID 31058846, 2019). "By contrast, high miR-31-5p expression regulates the chemoresistance of OXA after FOXC1 binds to the miR-31 promoter of miR-31-5p, which targets LATS2, leading to cancer growth and suppression of apoptosis in OR-LoVo cells." (PMID 31623173, 2019). "The miR-302/367/LATS2/YAP pathway is essential for maintenance of cancer stemness in PCa cells and promotes the development of castration resistance." (PMID 30935014, 2019). "The expression of LATS2 enhances cancer cell growth, angiogenesis, metastasis, and malignant transformation of oncogenic miRNAs." (PMID 31623173, 2019). "In line with the increased death upon LATS2 overexpression in human luminal cancer cells, mouse Lats2-CKO PyMT tumors displayed reduced numbers of CC3-positive cells, relative to WT-PyMT tumors." (PMID 30456386, 2018).
cancer (continued). "Several authors have noted promoter hypermethylation of MST1, MST2, LATS1, and LATS2 in various cancers." (PMID 30167083, 2018). "Next, we assessed the transcriptional impact of LATS2 modulation in cell lines derived from human luminal cancers." (PMID 30456386, 2018). "MiR-135b expression enhances cancer cell invasive and migratory abilities in vitro and promotes cancer metastasis in vivo by targeting multiple key components on the Hippo pathway, including LATS2, BTRCP and NDR2, as well as LZTS1." (PMID 28915579, 2017). "In the Hippo pathway, zyxin serves as a scaffold protein that stabilizes the interaction of Lats2 and Siah2, which results in Lats2 ubiquitination and degradation, leading to cancer cell migration and proliferation." (PMID 28928438, 2017). "To date, numerous miRNAs have been verified to target LATS2 and involved in Hippo pathway in diverse types of cancer, like miR-181b, miR-93, and miR-372." (PMID 29145896, 2017). "These condensates not only facilitate the sequestration of LATS2 but also enable its interaction with other cellular components, including YAP/TAZ, leading to the modulation of critical signaling pathways implicated in cancer development." (PMID 39757214, 2025). "YAP1 activation, accompanied by decreased LATS2 expression, has been reported in various cancers." (PMID 39247829, 2024). "Lats2 transcription and expression levels are highly sensitive to tumor suppressive signaling 5, modulate mitochondria-related apoptotic pathways 7, and influence cancer metastasis and invasion." (PMID 37497006, 2023). "Finally, LATS1/LATS2 knockdown can rescue the cancer cell killing effect from the combination treatment of AMG510 and IN10018, suggesting Hippo kinase signaling is involved in this FAK‐YAP related drug response." (PMID 34151545, 2021). "Although large tumor suppressor 2 (LATS2) is well accepted to be related to cancer progression, the prognostic potential and immune response role of LATS2 expression in CRC remain unclear." (PMID 34699318, 2021). "In summary, our data imply that LATS2 may act as a cancer suppressor gene and be correlated with clinical prognosis and immune infiltration in CRC." (PMID 34699318, 2021). "Interestingly, recent experiments have identified LATS2 as a novel regulator of cancer survival and invasion." (PMID 32554853, 2020). "Our data infer that a low LATS2 expression due to methylation may contribute to the cancer progression and could be useful for the diagnosis of OSCC." (PMID 32458634, 2020). "Whether ROCK1 promotes cancer cell viability by inhibiting LATS2 and subsequently blocking Bax- or JNK-induced mitochondrial apoptosis in NSCLC remains to be determined." (PMID 32554853, 2020). "LATS2 promoter hypermethylation is an important epigenetic silencing mechanism leading to cancer." (PMID 32458634, 2020). "Importantly, we reveal a novel drug-resistance mechanism in which the transcription factor FOXC1 binds to the miR-31 promoter to increase the expression of miR31-5p and regulate LATS2 expression, resulting in cancer cell resistance to OXA." (PMID 31623173, 2019). "Conversely, simultaneous activation of LATS2 and PPARγ may instigate a metabolic catastrophe, particularly in cancer cells with high energy demands, possibly by increasing mitochondrial burden." (PMID 30456386, 2018). "Dampening of PPARγ activity might reflect an energetic necessity of highly glycolytic LATS2-depleted cancer cells." (PMID 30456386, 2018). "Hence, to explore more directly the role of LATS2 in lumB cancer, we generated MMTV-PyMT mice with mammary-specific deletion of Lats2 (Lats2-CKO PyMT)." (PMID 30456386, 2018). "This may indicate that SIAH2-mediated regulation of LATS2 turnover may play an important role in this cancer." (PMID 29673168, 2018). "In contrast, most of the Lats2-CKO PyMT mice displayed full-blown carcinomas." (PMID 30456386, 2018).
cancer (continued). "Thus, we identified miR-31-mediated LATS2 signaling pathways to be involved in cancer EMT process, which is a pivotal step for ESCC metastasis." (PMID 29145896, 2017). "Similarly, hypermethylation of promoter also contributes to another tumor suppressor LATS2 downregulation in cancer cells." (PMID 28029651, 2017). "Our study demonstrates that Zyxin-Lats2–Siah2 axis may serve as a potential therapeutic target in cancer treatment." (PMID 27030211, 2016). "Recently, a potential role for LATS2 in cancer has been reported." (PMID 20932276, 2010). "Lats2 might have a role against cancer development, probably through the induction of senescence, and this could explain the link between its down-regulation and tumoral progression." (PMID 18800172, 2008). "LATS2 downregulation could promote cancer cell growth and migration." (PMID 35924072, 2022). "Consequently, it is necessary to determine the function of LATS2 in predicting and treating cancer." (PMID 36118851, 2022). "Moreover, the down-regulation of LATS2 by miR-372 prolonged the survival of esophageal squamous cell carcinoma, suggesting that miR-372 and miR-373 may act as oncogenes in cancer cells." (PMID 34575133, 2021). "However, the significance for LATS2 in cancer progression and immunology in CRC remains elusive." (PMID 34699318, 2021). "Furthermore, we found miR-31-5p could modulate Hippo pathway in Caco2 cells via repressing LATS2 although miR-31 was reported to target LATS2 in other cancers." (PMID 31275360, 2019). "Moreover, we reported for the first time that miR-31 could directly silence LATS2 expression inhibiting EMT in ESCC cancer cells." (PMID 29145896, 2017). "We found that MST1, LATS1, and LATS2 were consistently expressed at low levels in the cytoplasm of basal cells of the normal epithelium, dysplastic cells of the OED, and cancer cells." (PMID 38444414, 2024). "In turn, it was shown that the under-expression of LATS2 induced a high expression of CDK2, promoting the transition of cancer cells from the G1 to the S phase of the cell cycle." (PMID 37761387, 2023). "On the other hand, low SYNPO2 expression and mutation can activate signaling pathways such as the PI3K/AKT/mTOR and the LATS2/YAP/TAZ pathways, promoting cancer development." (PMID 37544991, 2023). "Strikingly, the results suggested that LATS2 expression and NRP1 expression were positively correlated in all 33 cancers." (PMID 34699318, 2021). "Specifically, the TCGA datasets were integrated to evaluate the correlations of LATS2 expression with the four specific immune cell gene markers (PTPRC, BCL6, NRP1, and THBD) in 33 cancer types." (PMID 34699318, 2021). "LATS2, MCC, DCC, RHOB, TRIM13, LIMD1, and GPC3 also strongly and positively regulated gene down-expression in cancer." (PMID 33580150, 2021). "Dasatinib shows the potential to modulate anticancer immunity, and selectively impairs LATS2-altered MPM cells, in line with the evidence that Dasatinib enhances anti-PDL1 efficacy in cancer." (PMID 32824422, 2020). "Hundreds of FOXP3 target genes have been identified in both Treg cells and cancer cells so far, including HER2/ERBB2, SKP2, CD44, BRCA1, p21, and LATS2." (PMID 30011797, 2018). "In this study, we reported that miR-31 acted as an oncogene in the development of ESCC by directly inhibiting LATS2 expression and ulteriorly stimulating TAZ, ultimately triggering EMT in cancer cells." (PMID 29145896, 2017). "It was recently demonstrated that Scribble interacted with Lats2 and TAZ to mediate the Hippo pathway and regulate cancer stem cell population." (PMID 26527679, 2016). "In particular, compared to the untreated group, the extract increased the expression of the tumor suppressor genes LATS2 and PTPN14 in HCT116 cells and decreased the expression of the oncogenes YAP1 and TEAD2 in HT29 cells, suggesting targeted modulation of cancer cell growth." (PMID 41516111, 2025).
cancer (continued). "Whereas previous studies have shown that Lats2 signaling promotes mitochondrial fission in cancer cells 10, this phenomenon has not been verified in cardiac tissue following AMI." (PMID 37497006, 2023). "Furthermore, LATS2 expression was positively correlated with the expression of PTPRC, BCL6, NRP1, and THBD in almost all cancers in the TCGA database." (PMID 34699318, 2021). "We evaluated the expression of LATS1 and LATS2 proteins by immunohistochemistry among the non-cardia GC tissues and normal tissues adjacent to cancer in our pre-study." (PMID 32423384, 2020). "The results showed that the expression of LATS1 and LATS2 in non-cardia GC tissue was significantly lower than that in normal gastric tissue adjacent to cancer." (PMID 32423384, 2020). "Interestingly, induction of Lats2 and phosphorylation of YAP regulate Taxol sensitivity in cancer cells." (PMID 26375055, 2015). "However, how cancer cells override the negative regulation induced by MST1, LATS2, MOB1, and SAV1 to exhibit constitutively inactivated Hippo signaling and activated YAP/TAZ remains puzzling." (PMID 26561204, 2015). "Although Hippo pathway activity is frequently suppressed, and the activity or expression of YAP and TAZ is elevated in cancer, it is important to note that the components of the central Hippo pathway cascade, including LATS1, LATS2, YAP, and TAZ, are not frequently mutated or deleted." (PMID 29673168, 2018). "Importantly, gene set enrichment analysis (GSEA) indicated that gene expression changes in Lats2-CKO PyMT tumors correlated with the transcription profile of human LATS2L lumB tumors, confirming the similarity of this mouse model to human lumB cancer." (PMID 30456386, 2018). "More broadly, the ability of LATS2 to modulate master regulators of lipid metabolism such as PPARγ and SREBP expands the functional consequences of the deregulation of Hippo pathway components in cancer and may indicate a metabolic Achilles' heel of particular tumors." (PMID 30456386, 2018). "Our study has used an unbiased bioinformatics analysis to identify a restrictive role of LATS1, but not LATS2, in Srf-induced autophagy in HCC and other cancer types and normal liver in vivo." (PMID 31848340, 2019).